TNF (tumor necrosis factor)
Diseases named in the same sentence as TNF in open-access papers (continued):
Sharing a sentence is not in itself a finding about the gene and the disease.
Hepatitis (continued). "Endothelial cells release IL-6, IL-8, and TNF-alpha, which contribute to thrombocytopenia, bleeding, and hepatitis." (PMID 41417343, 2025). "Both TNF-α and IL-6 are key pro-inflammatory cytokines, and their measurement confirms the presence of liver inflammation." (PMID 41155639, 2025). "SP effectively suppressed IKK, IκB, and p65 phosphorylation, modulated the NF-κB signaling pathway, downregulated IL-1β, IL-6, and TNF-α expression, and mitigated EtOH-induced liver inflammation." (PMID 40362898, 2025). "This leaked LPS exacerbates alcohol-induced liver inflammation and activates immune cells, triggering the release of pro-inflammatory cytokines like interleukins IL-1β, IL-6, and tumor necrosis factor-alpha (TNF-α)." (PMID 40860877, 2025). "TNF-α enhances inflammation and directly damages hepatocytes, and TNF-αgene polymorphism −308G/A is significantly associated with drug-induced hepatitis (OR: 1.95, 95% CI: 1.11–3.14)." (PMID 39533543, 2024). "The systemic inflammation observed in the patient reported here partially responded to treatment with anti-TNF agents, although mild hepatitis and neutropenia persisted." (PMID 39264518, 2024). "Prior to commencing anti-TNF-α treatment, screening tests, including hepatitis screening and chest radiography, were conducted to exclude TB." (PMID 39493161, 2024). "Demographic characteristics, pre- and post-treatment hepatitis markers, and laboratory parameters of patients receiving anti-tumor necrosis factor-alpha therapy in our rheumatology clinic were retrospectively examined." (PMID 39045935, 2024). "For example, it has been reported that the TLR4/NF-κB/MyD88 signaling pathway can induce the transcription and expression of a variety of pro-inflammatory chemokines, such as IFN-γ and TNF-α, related to liver inflammation." (PMID 38931473, 2024). "This action aligns with the BSR guidelines, which required the patient to undergo pre-anti-TNF-α screening that included hepatitis screening and a chest X-ray." (PMID 39493161, 2024). "Cd can activate the NLRP3 inflammasome, promoting liver inflammation and hepatitis, particularly severe during early estrus, by increasing TNF-α, MCP-1, and pro-inflammatory cytokines such as IL-1α, IL-1β, and IL-18." (PMID 39255638, 2024). "This study is consistent with previous findings on LPS-induced liver inflammation, confirming that LPS produces a potent inflammatory response that causes the elevation of CRP, IL-1β, and TNF-α." (PMID 39727984, 2024). "Liver inflammatory cytokines take part in the pathogenesis of hepatitis; tumor necrosis factor alpha (TNF-α) is one important factor that triggers hepatocyte apoptosis." (PMID 37833954, 2023). "The occurrence of both lupus-like syndrome and hepatitis following anti-TNF-α therapy in the same patient is infrequent." (PMID 37175894, 2023). "HDGF induces TNF-α/IL-1β/IL-6/COX-2 signaling in response to concanavalin A-induced hepatitis in vitro and in vivo." (PMID 37827291, 2023). "It is well known that TNF induction is one of the earliest events in hepatitis, triggering a series of other cytokines that cooperate to recruit inflammatory cells, kill liver cells, and initiate a wound-healing response." (PMID 37047287, 2023). "Other research has highlighted the role of inflammatory and/or immunomodulatory interleukins production by NKT cells (especially IFN-γ, IL-4, TNF-α, and IL-10) in the pathogenesis of ConA-induced hepatitis." (PMID 38132174, 2023). "Increasing levels of LPS activate Toll-like receptor 4 signaling pathways, produce proinflammatory cytokines, such as IL-17, TNF-α, IL-6, and IL-1β, and promote liver inflammation." (PMID 38138294, 2023). "In this study, BCG immunostimulation induced hepatitis, characterized by inflammatory cell infiltration to form large and small clumps, increased liver weight, increased TNF-α and IL-1β, and increased AST/ALT." (PMID 37833431, 2023).
Hepatitis (continued). "TNF has been shown to promote hepatitis in murine hepatitis virus (MHV) infection as Tnfr1−/− mice displayed less hepatic apoptosis and necrosis, and reduced neutrophil infiltration into the infected liver as well as prolonged survival." (PMID 35122118, 2022). "These later observations meant that in acute CCl4-induced hepatitis, TNF-α would help protect hepatocytes through both RIPK1-independent and dependent mechanisms." (PMID 35806372, 2022). "Studies have shown that IL-10 played an anti-fibrosis role in the Progression of liver inflammation and also played an important regulatory role on TNF-α." (PMID 36615846, 2022). "TNF-α, IL-1β, and IL-6 are crucial cytokines involved in the occurrence and development of liver inflammation." (PMID 36144271, 2022). "The induction of CCl4 further lures inflammation in the liver tissues, leading to the release of various inflammatory cytokines, such as tumor necrosis factor-alpha (TNF-α, IL-6, and IL-1β), and inflammatory regulators (Cox2 and iNOS), thus causing hepatitis." (PMID 35942372, 2022). "Among these mediators, IFN-γ and TNF-α play essential roles in the progression of Con A-induced hepatitis." (PMID 36239355, 2022). "These genes were significantly enriched in Influenza A, TNF signaling pathway, IL-17 signaling pathway, Hepatitis C, NOD-like receptor signaling pathway, Epstein-Barr virus infection, and Measles (P < 0.05)." (PMID 35277199, 2022). "Overproduction of inflammatory cytokines such as IL-1β, IL-18, IL-6, and TNF-α during the activation of IRI-induced immune responses is referred to as liver inflammation." (PMID 35978104, 2022). "In Timp3 knockout mice, TNF-α converting enzyme activity was increased, thereby providing excessive release of TNF and augmentation of TNF signaling in the liver, which induced hepatitis-like inflammatory reaction and regeneration failure." (PMID 35892823, 2022). "Previous research showed that Kupffer cells have vital importance to ConA-induced hepatitis with a tough TNF secretion ability." (PMID 36248904, 2022). "Ultimately, PLEKHO2-deficient mice display greatly increased hepatotoxicity and lethality after TNFα-induced hepatitis." (PMID 34272357, 2021). "In detail, some pathways related to CLI were obtained, including hepatitis B, TNF signaling pathway, apoptosis, hepatitis C, IL-17 signaling pathway, and hypoxia-inducible factor (HIF-1) signaling pathway." (PMID 33747110, 2021). "In the mathematical model developed in this study, we assumed that changes in the transaminase activities in the mouse serum reflect the progression of hepatitis and that both TNF-α and IFN-γ contribute to liver damage." (PMID 33919375, 2021). "TNF-α is also involved in the pathophysiology of hepatitis, also upon CD40 activation, including our own SBS model." (PMID 34440067, 2021). "Due to the production of a large number of reactive oxygen free radicals, oxidative stress will promote the release of inflammatory factors, such as IL-1β, IL-6 and TNF-α, which leads to liver inflammation." (PMID 34828972, 2021). "The results of earlier studies suggest that the inflammatory mediators IFN-γ, TNF-α, and IL-6 play a critical role in ConA-induced hepatitis as well as in the development of AIH in humans." (PMID 33919375, 2021). "Together, these results indicate that C14-Tri-LAN-Gly protects mice from TNF-α/D-GalN-induced lethal hepatitis by inhibiting hepatocyte apoptosis." (PMID 33746949, 2021). "Previous study indicates that garlic sulfur compound, allicin, attenuates TNF-α production and adhesion molecules expression in ConA-induced hepatitis and thus attenuates liver damage." (PMID 33809904, 2021). "Activated macrophages produce pro-inflammatory factors, such as TNF-α, IL-6, and IL-1β, which induce liver inflammation and injury." (PMID 35069557, 2021). "GAS6 deficiency has been reported to reduce the expression of TNF-α and MCP-1 and was suggested to prevent liver inflammation, steatohepatitis, and fibrosis in mice." (PMID 34734092, 2021).
Hepatitis (continued). "The progression of hepatitis is driven mainly by TNF-α and IFN-γ, which simultaneously contribute to the death of liver cells." (PMID 33919375, 2021). "ConA-induced hepatitis is mediated, at least in part, by the prototypic Th1 cytokines IFNγ and TNFα." (PMID 34305911, 2021). "TNF-α is a proximal mediator of hepatotoxicity in several models of hepatitis and liver damage including LPS/D-GalN." (PMID 33746949, 2021). "We also reported that this compound decreased the levels of TNF-α and activities of transaminases in immune-mediated ConA-induced hepatitis in mice, a commonly used animal model of AIH." (PMID 33919375, 2021). "In this study, we report the extent of tissue inflammation and metabolic alterations during CD40-mediated hepatitis as related to the TNF-α pathway in wt and TNFR1−/− mice in our established model of SBS." (PMID 34440067, 2021). "TNF inhibitors are also reported to increase the likelihood of hepatitis consequent to hepatitis B virus (HBV) reactivation; however, data on the specific increased risks vary between TNF inhibitors, from 12.5% to 62.5%." (PMID 33535498, 2021). "In the concanavalin A (ConA) model of hepatitis, both MA and EA attenuated TNF-α production in serum, but when VGX was conducted, the production of TNF-α elevated." (PMID 35095910, 2021). "NK cells in chronic HCV Hepatitis are characterized by a functional dichotomy, featuring enhanced cytotoxicity and reduced production of IFN-γ and TNF-α caused by altered IFN-α signaling." (PMID 32108916, 2020). "In liver, the endogenous H2 produced by intestinal flora had the ability to improve Concanavalin A (Con A)-induced hepatitis by decreasing serum TNF-α and IFN-γ, while inhibition of intestinal flora by antibiotics aggravated Con A-induced hepatitis." (PMID 32595504, 2020). "In the present study, we found that hVNS regulates hepatic expression of inflammatory cytokines TNF-α, IL-1β, and IL-6 in Con-A model of hepatitis and also increases the expression of ChAT gene in the DMV neurons." (PMID 33272194, 2020). "We provide further evidence that pharmacological targeting of LRH-1 results in reduced TNF-dependent hepatitis." (PMID 32111818, 2020). "Critical to the pathogenesis of liver damage in GalN/LPS-induced hepatitis is the expression of TNFα." (PMID 32260486, 2020). "The pathogenic roles of IL-1α, TNF-α, IFN-γ, and IL-6 in Con A-induced hepatitis have been extensively established in previous studies 39-42." (PMID 32641985, 2020). "In this study, we investigated the role of LRH-1 in the regulation of lipopolysaccharide (LPS)-induced pro-inflammatory cytokines in macrophages and in an in vivo model of macrophage- and TNFα-dependent hepatitis." (PMID 32111818, 2020). "In our study, the elimination of KCs completely protects against Con A-induced hepatitis by decreasing serum inflammatory cytokines such as IL-1α, TNF-α, IFN-γ, MCP-1, IL-12, and IL-6, relevant to Con A-induced hepatitis 39-42." (PMID 32641985, 2020). "In a model of hepatitis, artesunate treatment inhibited production of inflammatory cytokines such as interferon gamma and tumor necrosis factor alpha while driving production of the anti-inflammatory IL-1017." (PMID 31420579, 2019). "In several models of hepatitis mediated by TNF, it has been shown that only solTNF promotes liver necrosis but not tmTNF18." (PMID 30923339, 2019). "In a cyclophosphamide-induced liver inflammation model, rutin downregulated the TNF-α/IL-6 and NFκB/MAPK pathways to protect the liver." (PMID 30781895, 2019). "Our results provide the first evidence that Lgals3 deletion promotes MCMV-induced liver inflammation and enhances MCMV-induced hepatitis by facilitation of TNF-α-dependent hepatocyte death." (PMID 30800112, 2019). "MMP-8, also referred to as collagenase-2, is considered to play an essential role in the development of hepatitis in TNF-induced conditions." (PMID 31083413, 2019).
Hepatitis (continued). "Our data highlight the protective role of Gal-3 in MCMV-induced hepatitis by attenuation of TNF-α-mediated death of hepatocytes." (PMID 30800112, 2019). "ConA-induced hepatitis depends on the activation of T cells by macrophages in the presence of ConA, followed by the release of a variety of cytokines such as TNF-α and IFN-γ to mediate inflammatory liver damage." (PMID 31889917, 2019). "In ConA-induced hepatitis, TNFα and IFNγ are rapidly produced in response to ConA and induce the expression of pro-inflammatory proteins in both parenchymal and non-parenchymal liver cells." (PMID 30323351, 2018). "For example, higher concentrations of interleukin-1, interleukin-6, and tumor necrosis factor-α were found with several liver diseases, such as cirrhosis, hepatitis, and alcoholic liver disease." (PMID 30083134, 2018). "Both hepatitis models displayed significantly upregulated hepatocellular TNF and CCR10 protein expression." (PMID 29445190, 2018). "Injection of 0.4 μg TNF led to similar ALT levels as seen with a OT-I T cell-mediated hepatitis and half of the infectious dose of AdGOL." (PMID 30442932, 2018). "Tumor necrosis factor inhibitors (anti-TNF) increase the likelihood of hepatitis consequent to HBV reactivation, but reported risks and outcomes vary." (PMID 29694398, 2018). "The flavonoid, genistein, decreased levels of inflammation mediators, including IL-6, TNF-α by inactivation of NF-κB in alcohol-induced liver fibrosis in rats and LPS/D-GalN-induced hepatitis in mouse." (PMID 29922155, 2018). "Inflammatory cytokines, such as ROS and TNF-α, contribute to the development of hepatitis induced by Con-A." (PMID 29688069, 2018). "Some studies comparing patients with hepatitis B and C showed increased levels of plasma IFN-γ, TNF-α, and IL-2 in patients with hepatitis B14." (PMID 28928388, 2017). "With respect to ALF, CCR2−/− mice exhibit increased hepatic injury, with elevated IFN-γ and TNF-α expressions, in an acetaminophen-induced hepatitis model." (PMID 28272428, 2017). "As a critical proinflammatory cytokine, tumor necrosis factor-alpha (TNF-α) acts as a master switch in establishing the intricate link between hepatitis and HCC." (PMID 26683365, 2016). "We report a 34-year-old Caucasian man with one-decade history of TNF-blockade-responsive seronegative arthritis who presented with abrupt onset of fever, serositis, bicytopenia, splenomegaly, hepatitis, and disseminated intravascular coagulation." (PMID 27818826, 2016). "Together, these experiments demonstrated that TNF-α contributes to ConA-induced hepatitis, and is responsible for the apoptosis and hepatitis severity observed in the Ripk1LPC-KO mice." (PMID 27831558, 2016). "As the dominant factors in ConA-induced hepatitis, the levels of TNF-α and IFN-γ were detected by ELISA, real-time PCR, western blot and immunohistochemistry." (PMID 27035150, 2016). "In the Ripk1LPC-KO mice challenged with ConA, TNF-α triggers apoptosis, responsible for the observed severe hepatitis." (PMID 27831558, 2016). "Infected mice developed typical signs of hepatitis within 24–72 h post infection and during this period, pro-inflammatory cytokines, including interleukin (IL)-1β, IL-6, and tumor necrosis factor (TNF) α were secreted at the active sites of infection." (PMID 26739172, 2016). "Pro-inflammatory cytokines, especially tumor necrosis factor (TNF)-α, play critical roles in the occurrence and development of liver inflammation in ALF." (PMID 27448985, 2016). "As a critical proinflammatory cytokine, tumor necrosis factor-alpha (TNF-α) acts as a master switch establishing the intricate link between hepatitis and HCC." (PMID 27191988, 2016). "Proinflammatory cytokines play important roles in hepatitis, including TNF-α, IFN-γ, IL-2, and IL-6." (PMID 25821351, 2015). "They presented elevated parasitemia, high TNF serum levels, hepatitis and mild carditis, as well as a high mortality rate, which were partly reverted by anti-TNF therapy." (PMID 26090667, 2015).
Hepatitis (continued). "We studied the frequency of Tregs and cytokines (IL-10, IFN-γ, and TNF-α) production during Con A induced hepatitis and characterized therapeutic effects of citrus peel extract on liver injury." (PMID 25126542, 2014). "The important regulatory roles are played by adipokines including interleukin-1β, interleukin-6, tumor necrosis factor-α, monocyte chemotactic protein-1, and adiponectin, ultimately reducing hepatitis and decreasing serum alanine aminotransferase release." (PMID 24816278, 2014). "In all of these types of hepatitis, the TNF was produced by CD11b+ Kupffer cells in the early period (at 1 h) after the injection of reagents." (PMID 24667392, 2014). "The enhanced hepatitis injury over time was also reflected by the up regulation of serum TNF-α, IL-6, IL-12p70, and IFN-γ, with the peak concentration at the time point of 6 h, followed by a rapid decrease within 48 h." (PMID 24981055, 2014). "In contrast to the hepatic injury induced by either α-GalCer or CpG-ODN, CD68+ Kupffer cells and their ROS production induced by the TNF produced by CD11b Kupffer cells/macrophages are the final effectors in Con-A-induced hepatitis." (PMID 24667392, 2014). "Since the publication and selection bias cannot be avoided, a bigger and longer follow-up study is required to clarify the influence on hepatitis reactivation after anti-TNF-alpha treatment." (PMID 24343455, 2014). "Since we previously reported that TNF and/or FasL are involved in the pathogenesis of some experimental models of hepatitis, we examined the functions of TNF and FasL in CCl4-induced hepatitis." (PMID 24667392, 2014). "The hepatic injuries induced by α-galactocylceramide (α-GalCer) or bacterial-DNA motifs (CpG-ODN) are TNF/FasL-dependent hepatitis, and concanavalin-A (Con-A)-induced hepatic injury is a TNF/ROS-dependent hepatitis." (PMID 24667392, 2014). "FasL-expressing NKT cells and ROS-producing CD68+ Kupffer cells, both activated by the TNF produced by CD11b+ Kupffer cells, are the final effectors in these hepatitis models." (PMID 24667392, 2014). "We have shown that ethyl pyruvate is able to prevent Con A-induced hepatitis by down-regulating the production of inflammatory cytokines such as IL-2, IL-6, IL-1β and TNF-α." (PMID 24498418, 2014). "In the present study, we investigated how a HFCD affects the function of CD11b+ Kupffer cells, NKT cells and TNF/FasL-dependent hepatitis evoked by these cells, and discuss the possible role of these cells in human non-alcoholic steatohepatitis (NASH)." (PMID 23372642, 2013). "In fact in endotoxin-induced murine hepatitis models, E3330 attenuates the elevation of plasma TNF activity suggesting that E3330 protects mice from liver injury through the inhibition of TNF production." (PMID 23967134, 2013). "In the process of severe hepatitis, activation of Fas and TNF affects the severity of hepatocyte apoptosis." (PMID 24303082, 2013). "In this model, D-GalN can potentiate the acute toxicity of LPS, whereby LPS activates macrophages and kupffer cells to produce TNF-α, then induce hepatocyte apoptosis in the early stage of LPS/D-GalN–induced hepatitis in mice." (PMID 24143247, 2013). "When the IDO-KO mice were treated with α-GalCer, the production of TNF-α from the infiltrating macrophages in the liver was significantly accelerated, and thus led to the development of severe hepatitis." (PMID 24039933, 2013). "Sex bias has been demonstrated previously in concanavalin A immune-mediated hepatitis, in which female BALB/c mice develop more severe hepatitis and exhibit higher levels of plasma TNF-α, IFN-γ, and IL-4 than do males." (PMID 23577207, 2013). "Treatment with dimaprit, a specific H2 receptor agonist, reduced plasma TNF levels in mouse models of endotoxin shock (LPS challenge) and hepatitis (LPS plus galactosamine challenge)." (PMID 22384111, 2012).